CXCR4 (C-X-C motif chemokine receptor 4)
Diseases named in the same sentence as CXCR4 in open-access papers (continued):
Sharing a sentence is not in itself a finding about the gene and the disease.
tumor (continued). "Depletion of CXCR4 in U87 GBM cells blocked their growth as intracranial xenografts indicating that tumor cell CXCR4 is required for tumor growth in vivo." (PMID 22427929, 2012). "In order to determine the relative influence of CXCL12 and CXCR4 on other patient and tumour variables, known to affect prognosis, a multivariate analysis was performed using the Cox multivariate regression model." (PMID 22415233, 2012). "Preincubation of DU145 cells with anti-CXCR4 antibody before subcutaneous injection into NOD/SCID mice significantly delayed tumor growth, compared to cells treated with control antibody." (PMID 22359577, 2012). "In this scenario, CXCR4 antagonists will target neoplastic cells as well as the pro-tumor stromal microenvironment." (PMID 22399057, 2012). "CXCR4+ cells were found to have significantly higher tumorigenicity than CXCR4− cells (up to 3.8-fold increase in xenograft tumor growth)." (PMID 22359577, 2012). "CXCR4 is a key regulator of tumor invasiveness, progression, and metastasis, and CXCR4-positive CSCs appear to represent an invasive population with migratory activity." (PMID 22626610, 2012). "This is also in line with the theory that organs producing SDF-1 attract CXCR4+ tumor cells and form metastatic tumors analogous to the directed homing of leukocytes." (PMID 22871210, 2012). "To elucidate the underlying association between CXCL12/CXCR4 expression and clinicopathological features, we assessed MVD and MLVD in tumor tissues." (PMID 23181100, 2012). "Inhibition of CXCR4 with AMD3100 on the other hand leads to a significant reduction of primary tumor growth and a relevant reduction of overall metastatic spread and of micrometastatic lung metastases." (PMID 23082154, 2012). "CXCR4 interacts with CXCL12 to promote tumor cell proliferation, induce the expression of MMP2, and increase invasion and metastasis." (PMID 22537906, 2012). "After we confirmed that CAF-related SDF-1/CXCR4 and TAM-related CCL5/CCR5 expressions were changed under different ZHENG conditions, we next investigated an association between the altered tumor microenvironments and tumor growth." (PMID 22690248, 2012). "In particular, SDF-1/CXCR4 axis is enrolled in many functional aspects of tumour progression, such as angiogenesis, site-specific metastasization, proliferation and survival of neoplastic cells." (PMID 22417013, 2012). "CXCR4 is a specific receptor for the ligand SDF-1 (stromal-derived-factor-1, also called CXCL12), and the CXCR4/CXCL12 axis has been shown to be important for tumour progression in a high number of cancer types." (PMID 22518090, 2012). "Most models of CXCR4 functions in tumor focus on its potential role as a mediator of motility, invasiveness and metastatic behaviors." (PMID 22242160, 2012). "Among these receptors, CXCR4, the predominant SDF-1 receptor, is of particular importance in tumor biology, especially in tumor metastasis." (PMID 23039915, 2012). "This enhancement of invasion depends upon CXCR4 signaling and most likely occurs through activation of CXCR4 on macrophages, resulting in increased paracrine interactions with tumor cells in the tumor microenvironment." (PMID 22314082, 2012). "We found that integrin-mediated cell adhesion at ECM components can specifically induce redistribution of CXCR4 at tumour cell surfaces with formation of larger receptor clusters." (PMID 22253872, 2012). "We observed that tumor-infiltrating FoxP3+ T cells highly express CCR8 and CXCR4, chemokine receptors associated respectively with memory cells and tumors." (PMID 22292042, 2012). "SDF-1α and its specific receptor CXCR4 expressed on the membrane of tumor cells form the SDF-1α/CXCR4 chemokine axis, which plays a pivotal role in migration, invasion and metastasis of some malignant tumors including LLC." (PMID 23300882, 2012).
tumor (continued). "M402 and M-ONC 202 were tested in an SDF-1α induced chemotaxis assay, using Jurkat tumor cells which were shown to express high levels of CXCR4, the cognate receptor for SDF-1α." (PMID 21698156, 2011). "It has been heavily documented that CXCL12 is expressed in the bone microenvironment and creates migration and invasion paths for the tumor cells with CXCR4 expression." (PMID 22074556, 2011). "The hypoxia-associated marker carbonic anhydrase IX (CA9) and double FOXP3/CXCR4 staining were performed on sections from a subset of these cancers including 10 basal-like and 11 luminal cancers matched for tumour grade." (PMID 21521526, 2011). "The role of CXCR7 further clouds the picture when attempting to understand what is more important to target while grasping CXCL12's effect on both CXCR7 and CXCR4 in the same tumor microenvironment." (PMID 22295222, 2011). "Similar to the in vitro invasion results, CXCR4 overexpression significantly enhanced the motile behavior of MTLn3 cells within the primary tumor - about three-fold compared with MTLn3 JP cells (P < 0.005)." (PMID 22152016, 2011). "CXCL12 also acts on tumor cell proliferation and survival and, through its main receptor CXCR4, governs the migration of malignant cells and their invasion of the peritoneum, a major route for ovarian cancer spread." (PMID 21410972, 2011). "CXCR4 expression was also significantly correlated with the proliferative index (Ki67) and the type of relapse: liver metastases occurred in 59% of patients with high CXCR4 expression in their tumor, and in 28% of those with low CXCR4 (p = 0.016)." (PMID 24212636, 2011). "58% of primary tumor samples had membranous staining of CXCR4 predominate, versus 80% of lymph node metastases having cytoplasmic staining predominate." (PMID 22295222, 2011). "Inhibition of HIF-1α, CAIX, LOX, or CXCR4 to reduce the development and growth of tumour metastases represent rational therapeutic strategies to disrupt the metastatic process." (PMID 22128892, 2011). "Although it is still unclear what leads to the overexpression of CXCR4 in tumor cells, studies point to genetic and microenvironmental factors." (PMID 21880153, 2011). "Co- injection of 50 μg cyclo-(-d-Tyr 1-Arg 2-Arg 3-Nal 4-Gly 5) or AMD3100 (data not shown) per mouse significantly reduced the tumor uptake, thus demonstrating specificity of CXCR4-mediated tumor binding or [68Ga]2 c." (PMID 21780290, 2011). "The NF-κB mediated regulation of CXCR4 in the tumor cells was also tested in the virtual system and the predictions corroborated with the experimental results." (PMID 21880153, 2011). "While both groups of animals evidenced localized tumor development, only mice in the CXCR4+ group demonstrated liver metastases, suggesting an important role for CD133+ CXCR4+ pancreatic CSCs in metastasis formation." (PMID 21188169, 2011). "CXCL12 is a known chemokine described in invasion and cell migration and is a ligand of CXCR4, a chemokine receptor that promotes tumor migration and invasion." (PMID 21998659, 2011). "It is known that CXCR7, a second CXCL12 receptor, regulates TEM of CXCR4+CXCR7+ tumor cells towards a CXCL12 source." (PMID 21672222, 2011). "CXCR4 is hypoxia-inducible and CXCR4 expression on metastatic tumour cells induces homing of disseminated tumour cells to specific tissues that express high levels of the CXCR4-specific ligand stromal cell-derived factor-1α (SDF-1α/CXCL12)." (PMID 22128892, 2011). "CXCR7 and CXCR4 expressed on tumor cells significantly induced proliferation and migration in the presence of CXCL12." (PMID 22180778, 2011). "The CXCR4/CXCL12 receptor axis has been shown to play an important role in metastasis of CXCR4-expressing tumor cells to organs and tissues that produce high amounts of CXCL12 such as the liver, bone, lymph nodes, lungs, and brain." (PMID 21915267, 2011).
tumor (continued). "Looking at clinicopathologic factors, statistical significance was found upon analyzing either CXCR4 or VEGF with the tumor's TNM stage." (PMID 22295222, 2011). "The stimulus for this colonisation by ECs is likely to be SDF-1 via its receptor CXCR4 and/or its receptor CXCR7, which is highly expressed in tumour-associated blood vessels including those in GBM." (PMID 21587260, 2011). "CXCR4/CXCL12 axis has been shown to enhance tumor growth by modulating tumor stroma through activation of cancer-associated fibroblasts and recruitment of CXCR4-positive endothelial precursor cells, thereby enhancing angiogenesis." (PMID 21915267, 2011). "CXCR7 overexpression downregulated the effects of CXCR4 in motility within the primary tumor, intravasation, and spontaneous lung metastasis formation." (PMID 22152016, 2011). "Up-regulation of CXCR4 in Treg correlated with the basal-like phenotype (P = 0.029) and tumour hypoxia, as indicated by CA9 expression (P = 0.049)." (PMID 21521526, 2011). "Hypoxia is also known to increase chemokine receptor expression such as CXCR4 in numerous cell types and CXCR4/SDF1 also indirectly promotes the proliferation and migration of tumour cells and enhances tumour-associated angiogenesis." (PMID 21647363, 2011). "The location-based chemotaxic ability of CXCL12, combined with its affect on CXCR4-expressed cells, creates a microenvironment for tumor migration." (PMID 22295222, 2011). "We recently showed that, although it does not directly mediate cell migration, CXCR7 can regulate TEM of CXCR4+CXCR7+ tumor cells towards CXCL12, an effect that can be blocked by CXCR7-specific antagonists and the second CXCR7 chemokine ligand, CXCL11." (PMID 21672222, 2011). "Our understanding of the role of SDF-1 and CXCR4 in tumour recurrence post irradiation is largely gained from pre-clinical studies using mouse xenografts of human tumours." (PMID 21587260, 2011). "This is also suggested by data in the literature showing that the recruitment and retention of proangiogenic hematopoietic cells to sites of ischaemic tissue damage or to tumours is mediated by the interaction of the SDF-1 with CXCR4." (PMID 21587260, 2011). "CXCR4/SDF1 also indirectly promotes tumor metastasis by mediating proliferation and migration of tumor cells and enhancing tumor-associated angiogenesis." (PMID 20102637, 2010). "It has been shown that the overexpression of CXCR4 significantly correlate with metastasis and poor prognosis in different tumor types." (PMID 20380740, 2010). "In all of the patient biopsies, CD68-positive tumour-associated macrophages presented a mixed CXCL10 (M1)/CD163 (M2) pattern, expressed CXCR4, GM-CSF and HB-EGF, and some stained positive for CXCL12." (PMID 20946648, 2010). "Then we studied the correlation between CXCR4 expression in endothelial cells (vascular CXCR4 expression, vCXCR4) of tumour microvessels and various clinicopathological parameters." (PMID 20386750, 2010). "In support of this contention, we were able to show that concomitant expression of CXCL12 in tumour cells and CXCR4 in tumour microvessels correlated with local tumour growth and UICC-tumour stage." (PMID 20386750, 2010). "In the last years, several molecules able to target CXCR4 or CXCL12 have been developed to interfere with tumor growth, including pharmacological inhibitors, antagonists, and specific antibodies." (PMID 20049170, 2010). "SDF-1α/CXCR4 signalling contributed to tumor-promoting effect of systemic AT-MSC administration on A375 xenotransplants." (PMID 20509882, 2010). "When expressing both, CXCL12 in tumour cells and CXCR4 in tumour microvessels, these tumours also were highly significantly associated with higher T- and UICC-stages." (PMID 20386750, 2010). "Our results indicated that the expression of CXCR4 was mainly located in the membrane and cytoplasm of tumor thrombus cells, which is consistent with a previous report." (PMID 21110890, 2010).
tumor (continued). "In RCC, the loss of function of the Von Hippel Lindau (VHL) tumor supressor gene mediates up-regulation of CXCR4 which then promotes tumor spread and progression." (PMID 20819239, 2010). "We found that the median CXCR4 and SDF1 mRNA levels were 109 compared to 3 and 117 compared to 2 in the tumors compared to normal tissue, and the expression of CXCR4 correlated with tumor grade (p < 0.001, ANOVA)." (PMID 20102637, 2010). "In IHC staining, 77% of tumor cells were CXCR4 positive in the cytoplasm, including high and low CXCR4 expression (Figure 1A2)." (PMID 20181250, 2010). "In 8% of T1/pT2a tumours (4 of 52) and in 34% of T2b/T3/pT4 tumours (81 of 239) CXCR4 positive microvessels were detectable." (PMID 20386750, 2010). "CXCL12 binds to the widely expressed CXCR4 and regulates key aspects of development, stem cell motility and tumour metastasis to tissues with high levels of CXCL12." (PMID 20376365, 2010). "Our data also demonstrate the contribution of SDF-1α/CXCR4 signalling to AT-MSC-mediated A375 tumor growth." (PMID 20509882, 2010). "The finding that CXCR7 specifically scavenges CXCL12 suggests a critical function of the receptor in modulating the activity of the ubiquitously expressed CXCR4 in development and tumor formation." (PMID 20161793, 2010). "CXCR4-expressing tumor cells preferentially metastasize to tissues that highly express CXCL12, including the lung, liver, LN, and bone marrow." (PMID 20502531, 2010). "Since the CXCL12-CXCR4 axis plays a prominent role in tumourigenesis, promoting angiogenesis and migration of tumour cells to metastatic sites, we selected CXCL12 and its receptor CXCR4 for further analyses." (PMID 20386750, 2010). "Most of the CXCR4 positive tumour specimens only revealed a faint cytoplasmic CXCR4 immunoreactivity (category 1+, 44 cases, 15%)." (PMID 20386750, 2010). "In our study group, vascular CXCR4 expression correlated significantly with the extent of local tumour growth." (PMID 20386750, 2010). "Comparing CXCR4 expression with the local tumour extent, CXCR4-mRNA levels increased with the local tumour growth (p = 0.079)." (PMID 20386750, 2010). "In EOC ascitic fluid and blood of patients the reduction of migration responses of monocyte/macrophages expressing several chemokine receptors (CCR1, CCR5, and CXCR4) produced in the tumor microenvironment, has been described." (PMID 20049170, 2010). "The ability of tumour cells to invade and migrate has been ascribed to the up-regulation of matrix metalloproteases (MMPs) and chemotactic axis CXCR4/SDF-1." (PMID 20226009, 2010). "Another promising target whose expression correlates with advanced stage of disease is the chemokine receptor CXCR4, a key receptor in the crosstalk between tumor cells and their environment." (PMID 20819239, 2010). "CXCR4 is a seven transmembrane G protein-coupled chemokine receptor that is over-expressed in a variety of tumors and involved in tumor metastasis." (PMID 19323821, 2009). "In the univariate analysis, LN metastasis, poorly differentiated tumour and CXCR4 expression predicted poor survival and shorter DFS." (PMID 19352387, 2009). "Together, our in vitro and in vivo results suggest that HIF-1α promotes bone metastases by regulating factors such as CXCR4, which promotes tumor cell homing to bone and VEGF, which promotes angiogenesis." (PMID 19727403, 2009). "For this reason, CXCR4 was proposed to be responsible for enhanced malignancy of tumour cells in hypoxic areas." (PMID 19352387, 2009). "CXCR4 has been shown to be involved in the major aspects of cancer progression, tumor cell proliferation, metastasis, and angiogenesis, and its involvement in one or more of these processes has been demonstrated in several human malignancies." (PMID 20028517, 2009). "Our recent results provide a novel mechanism for CXCR4-mediated tumor growth and metastasis and establish a functional link between CXCR4/CXCL12 and CCR6/CCL20 pathways in tumor development." (PMID 19340288, 2009).
tumor (continued). "CXCR4 is expressed in malignant tumor cells whereas its ligand SDF-1 (CXCL12) is expressed mainly by cancer associated fibroblasts (CAF)." (PMID 19340288, 2009). ", but remarkably, almost completely abrogated tumor cell homing and invasion to the lung (‘Ab anti-CXCR4’)." (PMID 19325708, 2009). "In future studies, we will prospectively evaluate the prognostic significance of pan-cytokeratin/CXCR4-positive cells, and determine the mechanisms involved in the regulation of CXCR4 expression on tumor cells." (PMID 19563666, 2009). "Tumor cells from at least 23 different types of cancers of epithelial, mesenchymal and haematopoietic origin express CXCR4." (PMID 19340288, 2009). "For example, the administration of CXCR4-neutralizing antibody into tumor-bearing mice by Müller and colleagues inhibited lymph node and lung metastasis in a breast cancer metastasis model." (PMID 19671192, 2009). "The importance of the CXCR4/CXCL12 pathway in tumor development was further demonstrated by neutralizing the interaction between CXCL12 and CXCR4." (PMID 19340288, 2009). "Immunostaining for CXCR4 expression on these NSCLC tissue microarrays confirmed significant expression of CXCR4 on both tumor cells of primary tumors and metastatic lesions." (PMID 19563666, 2009). "Pro-metastatic genes (VEGF-A, MMP-9 and CXCR4) are up-regulated, and the tumor inhibitory gene (RECK) is down-regulated in xenograft tumors developing in presence of PICP." (PMID 19226458, 2009). "The predominant CXCL12 receptor is the CX chemokine receptor 4 (CXCR4), a protein frequently overexpressed on the surface of human tumour cells of epithelial origin." (PMID 19352387, 2009). "CXCR4 is expressed on a majority (>80%) of the tumor cells in either adenocarcinoma or squamous cell carcinoma lung tumor specimens (respectively)." (PMID 19563666, 2009). "Sixteen patients with NSCLC were enrolled to this study for the analysis of CXCR4 and pan-cytokeratin expression on circulating tumor cells." (PMID 19563666, 2009). "In future studies, we will prospectively evaluate the prognostic significance of pan-cytokeratin/CXCR4+ cells, and determine the mechanisms involved in the regulation of CXCR4 expression on tumor cells in a larger patient population." (PMID 19563666, 2009). "CXCL12-mediated tropism of malignant breast, lung, and other cancer cells for characteristic sites of metastatic disease has been attributed predominantly to signaling through receptor CXCR4 on tumor cells." (PMID 19484126, 2009). "In vivo experiments showed that intravenous injections of anti-CXCR 4 siRNA not only decreased the CXCR4 mRNA level to 10% of the control level, but also virtually blocked metastasis into the lungs and suppressed the primary tumor growth." (PMID 22649602, 2009). "High levels of SDF-1 are present in organs that are commonly invaded by metastasizing cells, such as the bones, and these high SDF-1 levels attract CXCR4-positive tumor cells." (PMID 19508713, 2009). "Comparison of nuclear- and cytomembrane-type CXCR4-positive CRCs revealed that the nuclear-type CRCs were significantly more likely to show poor differentiation, high tumour stage, and frequent LN metastasis." (PMID 18443596, 2008). "The findings underscore relevance for CXCR4 in migration of low metastatic BCCs into BM at low tumor burden, or for a specific population of BCCs during high tumor burden." (PMID 18575622, 2008). "The expression of CXCR4, confirmed in more than 23 solid cancers, was upregulated on the surface of tumour cells of epithelial origin." (PMID 19002187, 2008). "CXCR4 was expressed mainly in tumor cells, and it was also detected, but less intensely, in prostate hyperplasia (t = 3.86, P < 0.05)." (PMID 18983683, 2008). "This role ofCXCL12/CXCR4 is “commandeered” by cancer cells to facilitate thespread of CXCR4-bearing tumor cells to tissues with high CXCL12concentrations." (PMID 18779872, 2008).